H19 (H19 imprinted maternally expressed transcript)
Diseases named in the same sentence as H19 in open-access papers (continued):
Sharing a sentence is not in itself a finding about the gene and the disease.
breast cancer (continued). "H19 was said to have an oncogenic role in breast cancer cells in 2002, but has since been found to exhibit tumor suppressive action in vivo." (PMID 25849966, 2015). "One of the key proteins suppressed by Rb is E2F1, a transcription factor that binds to and activates H19 promoter, as was shown in breast cancer cells." (PMID 26536864, 2015). "Using a luciferase assay, we demonstrated that H19, through its microRNA, decreased both c-Cbl and Cbl-b expression in all breast cancer cell lines tested." (PMID 26353930, 2015). "We have previously shown that the H19 gene is activated by growth factors and increases breast cancer cell invasion." (PMID 26353930, 2015). "We showed that overexpression of H19/miR-675 enhanced the aggressive phenotype of breast cancer cells including increased cell proliferation and migration in vitro, and increased tumor growth and metastasis in vivo." (PMID 26353930, 2015). "Estradiol transcriptionally regulates H19, as treatment with estradiol of ovariectomized and adrenalectomized mice increases H19 expression in the uterus, as well as increasing its expression in breast cancer cell lines." (PMID 25400658, 2014). "Our integrative analysis of chromatin modifications with lncRNAs identified several lncRNAs that were associated with histone marks (e.g., H3K4me3 and H3K4me2 for H19) in normal breast tissue and breast cancer cell lines." (PMID 25296969, 2014). "H19 is upregulated in breast cancer, with over 70% of breast adenomas showing overexpression, and is significantly correlated with ER+ and PR+ breast cancers." (PMID 25400658, 2014). "Several direct lines of evidence indicate that H19 is involved in the metastatic process with its role being best characterized in bladder and breast cancer." (PMID 25101115, 2014). "The SNP lies close to the H19/IGF2 imprinted region, and the association of breast cancer with rs3817198 has been reported to be restricted to the paternally inherited allele." (PMID 23544014, 2013). "Loss of imprinting of IGF2 resulting in increased expression of IGF-2 is a common genetic alteration in human malignancies and aberrant methylation of IGF2/H19 locus has been detected in multiple human cancers including breast cancer." (PMID 23148692, 2012). "Six of the previously identified SNPs showed a statistically significant association with breast cancer risk: rs2981582 (FGFR2), rs3803662 (TNRC9), rs12443621 (TNRC9), rs889312 (MAP3K1), rs3817198 (LSP1) and rs2107425 (H19)." (PMID 22867275, 2012). "Studies from genomewide association studies (GWASs) in breast cancer reveal SNPs in five genes (TNRC9, FGFR2, MAP3K1, H19, and LSP1) are associated with breast cancer susceptibility in European population." (PMID 22778704, 2012). "Furthermore, lnRNA H19 plays a critical role in mediating drug resistance in breast cancer through the modulation of drug efflux, apoptosis, and miRNA interactions." (PMID 40142329, 2025). "For example, H19 can be used as a prognostic indicator for human breast cancer patients, but no such tumor diagnostic or prognostic markers have been identified in canines." (PMID 40643495, 2025). "Correlations of H19 pomorphisms with clinicopathological parameters in patients with breast cancer." (PMID 39267845, 2024). "Long non-coding RNA (lncRNA) H19 has gained significant recognition as a pivotal contributor to the initiation and advancement of gynecologic cancers, encompassing ovarian, endometrial, cervical, and breast cancers." (PMID 38166752, 2024). "Pearson’s χ2 test and corrective measures (age, menopausal status, and family history) were utilized, alongside unconditional logistic regression analysis, to explore the relationship between the genotypes of the H19 SNPs and clinical pathological parameters of breast cancer patients." (PMID 39267845, 2024). "We posited that increased levels of LincRNA H19 and miR-675 in breast cancer biopsies could serve as effective prognostic biomarkers." (PMID 39267845, 2024).
breast cancer (continued). "Finally, H19 is upregulated in multiple types of cancer, including gastric cancer, colorectal cancer, breast cancer, ovarian cancer, and glioma, and also correlates with poor prognosis in these cancers." (PMID 37713112, 2024). "Another intriguing avenue involves noncoding RNAs, as metformin may induce ferroptosis by inhibiting the autophagy process of lncRNA H19 in breast cancer." (PMID 38140764, 2024). "In breast cancer, H19 phosphorylates Akt and increases the level of Ser473 (phosphorylated Akt)." (PMID 38355574, 2024). "Studies have shown that highly expressed H19 in plasma could be a potential biomarker for the diagnosis of breast cancer and lung cancer." (PMID 39594687, 2024). "Among them, many regulatory associations have been revealed; for instance, miR-22 was demonstrated to inhibit ESR1 expression in breast cancer, whereas H19 could act as a sponge of miR-22 in many cell types (Gan, Lv & Liao, 2019; Sun, Mao & Ji, 2021)." (PMID 38549776, 2024). "Inhibition of H19 or ectopic expression of miR-200a could sensitize trastuzumab-resistant breast cancer cells." (PMID 39403602, 2024). "Similarly, H19 is released into the plasma from tumor cells upon breast cancer initiation, leading to an upregulation of plasma H19 levels." (PMID 38505593, 2024). "We postulated that H19 might be involved in the glycolysis process in GC cells given that H19 could control aerobic glycolysis in breast cancer stem cells and ovarian cancer cells." (PMID 37821504, 2023). "Therefore, we suggest SPRY4‐IT1, and H19 lncRNAs can be used as screening biomarkers for early detection of breast cancer." (PMID 36274054, 2023). "Considering that H19 is associated with poor prognosis and response to PARP inhibition in breast cancer, it was logically hypothesized that H19 might be involved in DSB repair." (PMID 37298108, 2023). "Furthermore, increased H19 expression was observed in patients with a poor prognosis and was correlated with the overall survival of breast cancer patients in the Kaplan–Meier Plotter database." (PMID 37298108, 2023). "These two lncRNAs, HOTAIR and H19, have been demonstrated to be overexpressed in breast cancer; this has been related with predictive value to assess resistance to neoadjuvant chemotherapy in breast cancer." (PMID 37108589, 2023). "This implied that H19 carried by EVs can influence adriamycin resistance in breast cancer cells." (PMID 37534210, 2023). "Therefore, it is apparent that H19 regulates breast cancer cell sensitivity to PARP inhibition via binding to ILF2." (PMID 37298108, 2023). "Moreover, repression of H19 levels in EVs potentiates the sensitivity of breast cancer cells to adriamycin." (PMID 37534210, 2023). "Higher H19 levels were correlated with PR positivity in breast cancer samples." (PMID 37298108, 2023). "Furthermore, evidence has been presented that H19 depletion increases sensitivity to PARP inhibitors via ILF2 in ER+ breast cancer cells with wild-type BRCA1 and in BRCA1 mutant triple-negative breast cancer cells." (PMID 37298108, 2023). "Therefore, further efforts to determine strategies to target H19 in breast cancer cells are warranted." (PMID 37298108, 2023). "In addition, there is a positive correlation between the levels of H19 and NBAT1 lncRNAs in breast cancer blood samples, and the possible association among their functions remain to be confirmed in further studies." (PMID 36274054, 2023). "Indeed, the overexpression of pre-miR-675 was able to mitigate the inhibitory effect of siRNA on H19 lncRNA in breast cancer cell line MCF-7." (PMID 37624037, 2023). "It was hypothesized that trastuzumab resistant HER2-positive breast cancer cells might be formed by downregulating Cbl through H19-derived miR-675." (PMID 36246634, 2022).
breast cancer (continued). "Another lncRNA, named 91H which located at the H19/IGF2 locus and transcribed in H19 antisense orientation, is overexpressed in breast cancer and prevent the maternal allele at the H19/IGF2 locus from DNA methylation, by this mechanism to induce overexpression of oncogenic H19." (PMID 36533073, 2022). "In addition, lncRNA H19 was found to upregulate Beclin-1 expression, thereby promoting autophagy and enhancing tamoxifen resistance in breast cancer cells." (PMID 36613528, 2022). "The present study suggests that metformin may induce ferroptosis by inhibiting autophagy via H19, and this discovery may facilitate the development of novel therapies for the treatment of breast cancer." (PMID 34644456, 2022). "In breast cancer, it was demonstrated that H19 inhibits SAHH, resulting in the accumulation of SAH, which restricts DNMT3B from methylating Beclin1 promoter and inducing the upregulation of Beclin1 and subsequently initiates autophagy, contributing to tamoxifen resistance." (PMID 35292092, 2022). "In breast cancer, abnormal expression of H19 may be related to tumor epidermal growth factor receptor 2 (HER2) positivity." (PMID 35506202, 2022). "H19 is a hypoxia-related lncRNA which regulates stem cells features in breast cancer." (PMID 36429127, 2022). "Overexpression of an ectopic H19 gene enhances the tumorigenic properties of breast cancer cells." (PMID 35563727, 2022). "Moreover, H19 is considered to contribute to breast cancer pathogenesis by several other mechanisms, including the regulation of miR-675 and interaction with c-Myc." (PMID 35328609, 2022). "E2F1 stimulates H19, which aids the G1-S transition in breast cancer cells." (PMID 36212140, 2022). "Increased expression of LINC00473 in HNSCC; LINC00114, MINCR and PVT1 in NPC; Linc-RA1 in glioma; LINC00473and CYTOR in NSCLC; NEAT1 and LINC00958 in cervical cancer; H19 in cardiac cancer; LINC02582 in breast cancer; and TUG1 in bladder cancer were associated with radioresistance." (PMID 36323697, 2022). "In addition, the knockdown of H19 suppresses cell growth by attenuating miR-138-mediated SRY-box transcription factor 4 (SOX4) suppression in breast cancer." (PMID 36613528, 2022). "HMGA1P6 and HMGA1P7, two pseudogenes of HMGA1 competing for endogenous RNA, can also lead to cancer when they are dysregulated, and the expression of HMGA1P7 is related to the levels of H19 and IGF2 in breast cancer, which is linked to the high double strand breaks in breast cancer cells." (PMID 35864955, 2022). "Compared to healthy tissues, H19 is upregulated in approximately 73% of breast cancer tissues." (PMID 34977037, 2021). "Recent studies have found that the H19/SAHH/DNMT3B axis may be critical for tamoxifen resistance in breast cancer patients and then decreasing methylation in the promoter region of Beclin1." (PMID 34199840, 2021). "Intercellular transfer of lncRNA H19 promoted doxorubicin resistance in breast cancer." (PMID 33821219, 2021). "However, our results contrast with data from breast cancer, in which lncRNA H19 overexpression promoted doxorubicin resistance by downregulating PARP1 expression." (PMID 34295821, 2021). "In addition, H19 also affects a series of other human diseases, including pulmonary fibrosis, retinoblastoma, breast cancer, colorectal adenocarcinoma, coronary artery disease, acute myelocytic leukemia, and so on." (PMID 34130625, 2021). "Similarly, in the TGCA breast cancer cohort (Figure 4Bii), a strong positive correlation (Pearson: 0.64) was also seen in the co-expression of H19 and IGF-II (p < 0.001) with 994 patients." (PMID 33669311, 2021). "It was found that LncRNA H19 could induce autophagy and suppress epithelial-mesenchymal transformation in breast cancer by targeting the let-7 miRNA family." (PMID 33796128, 2021).
breast cancer (continued). "In sum, current evidence establishes H19 as a potential breast cancer biomarker." (PMID 34527584, 2021). "Recently, increasing evidence has indicated that H19 expression is significantly associated with abnormal Wnt/β-catenin signaling pathways in various types of human cancers, such as pancreatic cancer, CRC, glioma, breast cancer, and bladder cancer." (PMID 34977037, 2021). "LncRNA H19 could promote drug resistance in HR+ breast cancer cells through inhibiting BIK and NOXA expression." (PMID 34938660, 2021). "H19 also promotes sphere formation by pluripotent CSCs produced from human mammary epithelial MCF-10A cells and its expression is associated with reduced disease-free and overall survival in breast cancer patients." (PMID 33799834, 2021). "In addition, lncRNA H19 knockdown inhibits breast cancer cell proliferation and induces apoptosis by regulating miR-130a-3p/SATB1." (PMID 34081618, 2021). "However, reactivation of H19 expression has been detected in many adult malignant tumors, including breast cancer, lung cancer, and bladder cancer." (PMID 32978516, 2020). "The long non-coding RNA H19, the precursor of miR-675, is involved in breast cancer development." (PMID 32610610, 2020). "A previous study speculated that the overexpression of H19 in breast cancer cells lines facilitates cell cycle transition G1/S while downregulation of H19 by RNA interference impedes S-phase entry and proliferation." (PMID 32345117, 2020). "It has been observed that exosomal H19 decreases in patients with breast cancer post‐surgery." (PMID 32924276, 2020). "Knockdown of H19 sensitized breast cancer cells to doxorubicin by promoting PARP1 upregulation." (PMID 32345117, 2020). "Additionally, H19 has been proposed to play vital function in many cancers, including colorectal cancer, gastric cancer, hepatocellular cancer, breast cancer, cervical cancer and lung cancer." (PMID 32281297, 2020). "However, the biological role of H19 in predicting postsurgical chemotherapy response in patients with breast cancer and on doxorubicin chemoresistance in breast cancer cells remains poorly understood." (PMID 32345117, 2020). "LncRNA H19 contributes to breast cancer cell growth and stemness through modulating let-7." (PMID 32437330, 2020). "Interestingly, hormone therapy drugs such as tamoxifen or fulvestrant elevate H19 expression in ERα-positive breast cancer cells, which contributes to the acquired resistance to these drugs." (PMID 33123488, 2020). "It has been reported that H19 affect EMT by functioning as miRNA sponges in breast cancer." (PMID 32698890, 2020). "Finally, we demonstrated for the first time that miR-675, like its precursor H19, increases the stemness properties of breast cancer cells." (PMID 32610610, 2020). "In breast cancer, our team showed that both H19 and its miR-675 are involved in CSC enrichment." (PMID 33291403, 2020).
breast cancer (continued). "Other studies have suggested that H19 acts as an miR-675-5p and miR-340-3p sponge to induce breast cancer cell apoptosis and promote epithelial-mesenchymal transition in paclitaxel-resistant breast cancer cells, respectively." (PMID 33318294, 2020). "H19 acts as an oncogene in bladder cancer, breast cancer, and hepatocellular carcinoma." (PMID 31956395, 2020). "Indeed, we show that both H19 and miR-675 participate in the migration, invasion and stemness of breast cancer cells." (PMID 32610610, 2020). "However, it has been shown that LIN28 also suppresses let-7 production, and that H19 can be downregulated by its own target let-7 in breast cancer cells." (PMID 33291403, 2020). "For each stem cell signature tested, we observed a higher expression of H19 in tumors expressing the signature, suggesting that lncRNA H19 may play a role in breast cancer stem cells." (PMID 32610610, 2020). "Thus, modulation of ERα expression can influence H19 expression, thus altering paclitaxel resistance in breast cancer cells." (PMID 32759784, 2020). "Furthermore, it was revealed that H19 negatively regulated PARP1 expression in breast cancer cells following doxorubicin treatment." (PMID 32345117, 2020). "Altogether, our data suggest that H19 and miR-675 could enhance the aggressiveness of breast cancer cells through both common and different mechanisms." (PMID 32610610, 2020). "H19 acts as ceRNAs both for miR-17-5P in thyroid cancer and for miR-152 in breast cancer." (PMID 33330574, 2020). "For instance, H19 sponges miR-let7 to maintain the breast cancer stem cells status." (PMID 32610610, 2020). "Highly expressed H19/low miR-675 and low NEAT1/high miR-204 could differentiate breast cancer subtypes and could be considered as diagnostic and therapeutic biomarkers." (PMID 32190687, 2020). "In addition, our results indicate that the overexpression of H19 and miR-675 observed in cancer cells is accompanied overall with an overexpression of different stem cell markers such as Sox2, Oct3/4 and Abcg2 in breast cancer cell lines." (PMID 32610610, 2020). "For instance, HOTAIR is a miR-148a sponge that regulates Slug to promote EMT expression in esophageal cancer, lincRNA-ROR induces EMT through ZEB regulation by inhibition of miR-205 in breast cancer and H19 operates as a sponge for let-7 to increase HMGA-2 mediated EMT in pancreatic cancer." (PMID 32575745, 2020). "Recently H19 has been shown to be upregulated in paclitaxel-resistant breast cancer cells, and knockdown of H19 might restore chemo-sensitivity in paclitaxel-resistant breast cancer cells." (PMID 32345117, 2020). "For instance, estradiol (E2) treatment enhances H19 expression in breast cancer cells." (PMID 33291403, 2020). "It is logical to predict that H19 could be a potential biomarker and that the inhibition ofH19 may be a candidate strategy for new breast cancer therapies." (PMID 32345117, 2020). "The previous study has shown that H19 was closely associated with stem cell phenotype in ALDH1‐positive breast cancer and was involved in poor prognosis in triple‐negative breast cancer." (PMID 32281297, 2020). "In this context, lncRNA H19 might be of special interest, as it is considered both a driving force of tumorigenesis and metastasis of breast cancer." (PMID 32514245, 2020). "SPRY4-IT1, GAS5, PANDAR and H19 are lncRNAs dysregulated in breast cancer." (PMID 33291485, 2020). "The role of H19 in the balance between both epithelial and mesenchymal phenotypes has also been shown by our team in the breast cancer model: thus, the mechanisms described in hepatocellular carcinoma could be transposed in the regulation of breast CSCs." (PMID 33291403, 2020). "For example, the H19 gene induced the epithelial to mesenchymal transition (EMT) in colorectal cancer; HOTAIR expression is closely associated with breast cancer metastasis and the high expression of HOTAIR is a powerful predictor of eventual metastasis and death." (PMID 32714183, 2020).